KCNA1 (potassium voltage-gated channel subfamily A member 1)
Diseases named in the same sentence as KCNA1 in open-access papers (continued):
Sharing a sentence is not in itself a finding about the gene and the disease.
epilepsy (continued). "One of the most promising transgenes for treating epilepsy is the engineered potassium channel (EKC), a mutant version of KCNA1." (PMID 39937026, 2025). "Interestingly, the effects of the ketogenic diet have also been researched in animals with mutations in the potassium channel gene KCNA1, but to our knowledge, people with KCNA1‐associated epilepsy (hereon referred to as KCNA1 epilepsy) are not treated with this dietary regimen." (PMID 37594756, 2024). "Previous research has shown that three of the four key potassium channel genes (KCNA1, KCNA2, KCNJ11, and KCNS1) play vital roles in seizures and epilepsy." (PMID 37483435, 2023). "Studies have shown that KCNA1 targeted deletions result in TLE and sudden death in animal models of epilepsy." (PMID 37483435, 2023). "KCNA1−/− mice display early seizures and premature unexpected death, and can be used as a valuable sudden unexpected death (SUDEP) model in epilepsy." (PMID 33569037, 2020). "We direct our attention to the possible influence of the KCNA1, KCNA2, and KCNV2 genes on the pathogenesis of epilepsy and responsiveness to treatment involving common drugs." (PMID 30441785, 2018). "Epilepsy is a frequently occurring comorbidity in people with EA1, but KCNA1 mutations in some people also cause epilepsy without causing EA1." (PMID 37594756, 2024). "There is evidence of altered brain glucose metabolism in people with Dravet syndrome based on studies with FDG‐PET, but there are no human studies on brain metabolism in KCNA1 epilepsy." (PMID 37594756, 2024). "Moreover, the use of α-T was found to reduce seizures in the Kainate (KA) model and in a model of Sudden Unexpected Death in Epilepsy, the KV1.1−/− (KV1.1, potassium voltage-gated channel subfamily A member 1) model." (PMID 27983697, 2016). "To further test the generality of the hypothesis that ASO-mediated inhibition of mTORC2 can suppress seizures across a wide range of causative etiologies, we studied two genetic models of spontaneous recurrent seizures: Kcna1-null mice and a “humanized” MTOR gain-of-function model of epilepsy." (PMID 37963879, 2023). "Over half of KCNA1 variants result in EA1, either with or without epilepsy." (PMID 37008993, 2023). "Interestingly, they showed that the Kcna1‐dCas9A construct had no adverse effect in the mouse hippocampi and rescued the hippocampal functions impaired due to epilepsy." (PMID 34486831, 2022). "A specific therapy to treat EA1 and epilepsy phenotypes caused by KCNA1 mutations is lacking and pharmacological technologies targeting Kv1.1 channels would be ideal to overcome the limits of available therapeutic options and to offer patients a personalized therapy." (PMID 32331416, 2020). "This breed had the lowest overall average heterozygosity and results for eleven genes, three of which are human epilepsy-associated (GABRD, KCNA1, and ME2), could not be determined due to low heterozygosity." (PMID 21518446, 2011). "In a study exploring the efficacy of anti-sense oligonucleotide (ASO) therapy for the treatment of epilepsy, a reduction in Scn8a brain expression levels by ASO was found to extend the lifespan and delay SUDEP onset in Kcna1 KO mice; however, seizure burden was not significantly improved." (PMID 37240170, 2023). "However, the effects of the KCNA1, KCNA2, and KCNV2 genes on epilepsy development and the effectiveness of AEDs are not yet clear." (PMID 30441785, 2018).
episodic ataxia type 1 (62 papers, 2011 to 2025). A frequent form of hereditary episodic ataxia characterized by brief episodes of ataxia, neuromyotonia, and continuous interictal myokymia. "KCNA1 mutations are primarily associated with a rare movement disorder known as episodic ataxia type 1 (EA1), and have also been linked to epilepsy." (PMID 41008569, 2025). "Genetic conditions associated with muscle twitching include rippling muscle syndrome caused by caveolin-3 (CAV3) mutations and episodic ataxia type 1 linked to mutations in the potassium channel gene KCNA1." (PMID 40718168, 2025). "Mutations in the KCNA1 gene, encoding the voltage-gated potassium channel Kv1.1, have been associated with a spectrum of neurological phenotypes, including episodic ataxia type 1 and developmental and epileptic encephalopathy." (PMID 35897654, 2022). "The KCNA1 gene is well-known to scientists because several mutations in this gene have been associated with episodic ataxia type 1 (EA1), a rare disorder of cerebellar origin characterized by recurrent episodes of ataxia and myokymia since early childhood." (PMID 35897654, 2022). "Kcna1 is associated with a rare neurological movement disorder known as episodic ataxia type 1 (EA1)." (PMID 36011327, 2022). "Mutations in the KCNA1 causes episodic ataxia type 1, which is characterized by interepisodic muscle weakness." (PMID 33804959, 2021). "Mutations in KCNA1 have been classically associated with episodic ataxia type 1 (EA1), a movement disorder triggered by physical and emotional stress." (PMID 33466780, 2021). "Mutations in KCNA1, which encodes Kv1.1, cause episodic ataxia type 1 (EA1), typically characterized by seizures, myokymia and ataxia." (PMID 34769301, 2021). "Loss-of-function missense mutations in the KCNA1 gene are primarily associated with episodic ataxia type 1 (EA1), an autosomal dominant neurological disorder characterized by ataxia and muscle rippling." (PMID 34312446, 2021). "Mutations in KCNA1 have been originally associated with episodic ataxia type 1 (EA1), a rare neurological movement disorder characterized by recurrent episodes of ataxia and myokymia since early childhood." (PMID 33466780, 2021). "KCNA1 mutations are primarily associated with a rare neurological movement disorder known as episodic ataxia type 1 (EA1)." (PMID 32316562, 2020). "Heterozygous mutations in the ion channel KCNA1 cause episodic ataxia type 1 (EA1), a disorder characterized by brief episodes of ataxia (seconds to minutes), accompanied by involuntary muscle movement (Myokymia)." (PMID 32466254, 2020). "Pathogenic KCNA1 variants have been linked to episodic ataxia type 1 (EA1), a rare neurological syndrome characterized by continuous myokymia and attacks of generalized ataxia that can be triggered by fever, abrupt movements, emotional stress, and fatigue." (PMID 32705822, 2020). "KCNA1 is the only gene that has been associated with episodic ataxia type 1 (EA1), an autosomal dominant disorder characterized by ataxia and myokymia and for which different and variable phenotypes have now been reported." (PMID 32331416, 2020). "The primary disease associated with KCNA1 mutations is episodic ataxia type 1 (EA1), a rare neurological movement disorder." (PMID 32316562, 2020). "Diverse heterozygous point mutations of KCNA1 with generalized or partial seizures have been reported in episodic type 1 ataxia, a neurological disorder characterized by attacks of generalized ataxia and spontaneous muscle tremors." (PMID 30441785, 2018). "Multiple heterozygous KCNA1 point mutations have been associated with generalized or partial seizures in episodic ataxia type 1." (PMID 30441785, 2018). "We have identified a novel heterozygous mutation in the KCNA1 gene of a young proband displaying typical signs and symptoms of Episodic Ataxia type 1 (EA1)." (PMID 28676720, 2017). "Episodic ataxia type 1 (EA1) is caused by loss-of-function mutations in the voltage-dependent potassium channel gene KCNA1." (PMID 27242528, 2016).
episodic ataxia type 1 (continued). "In episodic ataxia type 1, mutations in the KCNA1 gene occur resulting in defective Kv1.1 channels, increased neuronal excitability, prolongation of action potentials and in some cases deafness." (PMID 26082693, 2015). "For example, in the brain, mutations in KCNA1, the gene encoding Kv1.1, are associated with episodic ataxia of type 1,3 whereas dysfunction of Kv1.2 is associated with cerebellar ataxia." (PMID 22473914, 2012). "Another KV channel that has been linked to episodic ataxia type 1 (EA1) is the KCNA1 (KV1.1)." (PMID 38827782, 2024). "Additionally, we simulated the effects of specific episodic ataxia type 1 associated (EA1) KCNA1 mutations." (PMID 37292138, 2023). "Additionally, we simulated the effects of known mutations in KCNA1 gene encoding the KV1.1 potassium channel subtype associated with episodic ataxia type 1 (EA1)." (PMID 37292138, 2023). "Mutations in KCNA1 are mostly associated with episodic ataxia type 1 (EA1)." (PMID 38003469, 2023). "Thus, starting in 1994, episodic ataxia type 1 (EA1) was associated with mutations in the gene KCNA1 which codes for one of the units of the potassium channel." (PMID 33833732, 2021). "KCNA1 mutations cause episodic ataxia type 1 with myokymia (EA1)." (PMID 21858020, 2011). "Mutations in the KCNA1 gene, encoding for the alpha subunit of the voltage‐gated potassium channel Kv1.1, in humans can produce a broad spectrum of phenotypes but most commonly lead to development of episodic ataxia type 1 (EA1), a rare neurological movement disorder." (PMID 37594756, 2024). "Dominantly inherited missense mutations of the KCNA1 gene, which encodes the KV1.1 potassium channel subunit, cause Episodic Ataxia type 1 (EA1)." (PMID 37408217, 2023). "Mutations in the KCNA1 gene can lead to the development of episodic ataxia type 1 (EA1), an autosomal dominant disorder with multiple symptoms, most prominently episodes of cerebellar ataxia and myokymia." (PMID 36884287, 2023). "Episodic ataxia type 1 (EA1) is a rare autosomal potassium channelopathy, due to mutations in KCNA1." (PMID 35655106, 2023). "Heterozygous mutations in KCNA1 gene are responsible for episodic ataxia type 1 syndrome (EA1; OMIM # 160120)." (PMID 33613193, 2021). "Episodic ataxia type 1 (EA1) is caused by mutations in the KCNA1 gene encoding the voltage-dependent potassium Kv1.1 channel." (PMID 34208776, 2021). "In a recent article, we reported a novel heterozygous mutation in the KCNA1 gene of a proband affected by episodic ataxia type 1 (EA1)." (PMID 29973872, 2018). "Heterozygous mutations in the KCNA1 gene, encoding the Kv1.1 α subunit, were associated with episodic ataxia type 1 (EA1), a dominantly inherited disorder characterized by generalized ataxia attacks and spontaneous muscle quivering." (PMID 27064559, 2016). "Mutations in the KCNA1 gene induce LOF defects and change the biophysical properties of heteromeric Kv1 channels, causing epilepsy or Episodic Ataxia Type 1 (EA1) or a mixed phenotype." (PMID 39513870, 2024). "Episodic ataxia type 1, a condition characterized by seizures, ataxia, and myokymia, has been reported to be caused by mutations in the gene KCNA1, which codes for Kv1.1." (PMID 38474421, 2024). "Episodic ataxia type 1 (EA1) was the first discovered KV channelopathy and is caused by missense mutations in the KCNA1 (Kv1.1) gene." (PMID 37487086, 2023). "Heterozygous variants in KCNA1 (KV1.1; MIM 176260) have been linked to episodic ataxia type 1 (EA1, MIM 160120), sometimes associated with myokymia or (less commonly) seizures." (PMID 36318112, 2023). "Episodic Ataxia Type 1 (EA1) is an inherited, autosomal dominant disease caused by sequence variants in KCNA1, which encodes the voltage-gated potassium channel, KCNA1 (Kv1.1)." (PMID 36016548, 2022).
episodic ataxia type 1 (continued). "After the initial description of the syndrome by Van Dyke and colleagues in 1975, genetic linkage studies localized the episodic ataxia type 1 [EA1; OMIM 160120] locus to chromosome 12p13 and subsequently, mutations in single exon KCNA1 gene have been identified as the underlying cause of EA1." (PMID 32331416, 2020). "We have previously reported highly stereotypic changes in the excitability of motor axonsin the median nerve of patients with episodic ataxia type 1 (EA1), which is caused byloss-of-function mutations of the potassium channel gene KCNA1." (PMID 26912519, 2016). "In patients with episodic ataxia type 1 (EA1), mutations in KCNA1 gene result in alterations in fast K+ channel function." (PMID 26331047, 2015). "Intriguingly, only one mutation (identified with linkage in a large pedigree) in KCNA1 has been associated with hypomagnesemia, while all other KCNA1 mutations known to date cause episodic ataxia type 1 without hypomagnesemia." (PMID 27234911, 2017). "Episodic ataxia type 1 (EA1), a Shaker-like K+channelopathy, is a consequence of genetic anomalies in the KCNA1 gene that lead to dysfunctions in the voltage-gated K+ channel Kv1." (PMID 30140249, 2018).
Ataxia (38 papers, 2005 to 2025). Ataxia refers to impaired coordination of voluntary muscle movement. "Carbamazepine improved the severity of myokymia, in addition to ataxia, in a patient with a novel KCNA1 mutation." (PMID 37008993, 2023). "Of interest, childhood-onset genes with the highest cerebellar molecular layer interneuron cell-type expression were associated with ataxia syndromes manifesting partially or fully with seizures (e.g. KCNA1 and RORA)." (PMID 36624280, 2023). "Episodic Ataxia 1 (EA1) is an autosomal dominant inherited form of ataxia caused by genetic variation in the human KCNA1 gene, which encodes the KCNA1 (Kv1.1) voltage-gated potassium (Kv) channel." (PMID 36016548, 2022). "EA1, which features persistent myokymia and usually brief ataxia episodes, is caused by mutations in the KCNA1 gene, encoding the neuronal potassium channel Kv1.1." (PMID 32466254, 2020). "In contrast to other forms of episodic ataxia associated with KCNA1 (EA1) or CACNA1A (EA2), ataxia occurred after minor head trauma and acute cerebellar diffusion restriction together with late T2-hyperintensities was visible on MRI." (PMID 33126500, 2020). "Of these, 3 variants (p.Val1325Phe in SCN2A, p.Arg756His in ATP1A3, and p.Arg167Met in KCNA1) overlap with those identified from the analysis of the ataxia-related genes identified in Tier-1." (PMID 32466254, 2020). "Furthermore, in a mouse model of ataxia (Kcna1‐KO), exhibiting enlarged hippocampus and aberrant adult neurogenesis, the levels of Slc7a11 mRNA are increased." (PMID 38757355, 2024). "For instance, next-generation sequencing recently revealed an already known KCNA1 mutation (p.N255D) in a patient diagnosed with myotonia, presenting with hand and facial stiffness without ataxia." (PMID 34208776, 2021). "EA is a clinically heterogeneous disorder characterized by recurrent spells of ataxia lasting minutes to hours which has been associated over time to a number of genes besides CACNA1A and KCNA1 (CACNB4, SLC1A3, FGF14, SLC2A1, ATP1A3, PRRT2) accounting for the majority of cases." (PMID 32823520, 2020). "In unique cases, KCNA1 mutations have been associated with myokymia or neuromyotonia without ataxia." (PMID 32316562, 2020). "In this study, we conducted next-generation sequencing in Korean EA patients to identify pathogenic mutations of five known EA genes (KCNA1, CACNA1A, CACNB4, SLC1A3, and UBR4), and explored candidate genes that cause EA as a secondary phenotype or cerebellar ataxia." (PMID 29062094, 2017). "Since many patients showed the recurrent episodes lasting several hours, we could not detect KCNA1 mutation resulting in EA1 characterized by brief episodes of ataxia." (PMID 29062094, 2017). "This may be why KCNA1 and CACNA1A are more likely to present with ataxia than GLUT-1." (PMID 37008993, 2023).
episodic ataxia (30 papers, 2011 to 2026). "This case expanded the genetic and clinical spectrum of episodic ataxias and can suggest the involvement of the KCNA1 mutation in the development of asterixis." (PMID 38541088, 2024). "The KCNA1 gene encodes Kv1.1 voltage-gated potassium channel α subunits and has been linked to human disease since the 1990s when it was identified as the causative gene for an episodic ataxia and myokymia syndrome." (PMID 37240170, 2023). "LOF variants in KCNA1 encoding the KV1.1 channel resulted in an enhancement of GABAergic inhibition on Purkinje neurons reducing their spontaneous firing leading to episodic ataxia." (PMID 38251463, 2023). "The importance of Kv1.1 is underlined by the fact that mutations in the KCNA1 gene, coding for the α subunit of Kv1.1, lead to episodic ataxia with myokymia (rippling of muscles)." (PMID 33059680, 2020). "Genetic loci and clinical features of familial episodic ataxias have been defined in linkage disequilibrium studies with mutations in neuronal genes KCNA1 and CACNA1A." (PMID 22379397, 2011). "Exercise aggravated the episodic ataxia in the patient with KCNA1 mutation since age 3 years." (PMID 35719373, 2022). "In mice, Kcna1 deletion and missense mutations cause increased basket cell excitability leading to excessive inhibition of Purkinje cells, which can lead to stress‐induced motor dysfunction resembling the episodic ataxia in humans due to KCNA1 mutations." (PMID 33484493, 2021). "Familiar episodic ataxias are rare cause of recurrent vertigo, but molecular genetics has identified several mutations on KCNA1 and CACNA1A genes that suggest a key role for voltage-gated channels and solute carriers in the plasma membrane of neurons in recurrent vertigo." (PMID 22379397, 2011). "Mutations in KCNA1 may result in seizures, episodic ataxia and myokymia syndrome (MIM 160120)." (PMID 24699272, 2014). "Kv1.1 channels located at juxtaparanodes have a profound stabilizing effect on the action potential when it reaches the transition zone near the nerve terminal, and mutations in KCNA1 encoding Kv1.1 cause episodic ataxia and myokymia [reviewed in]." (PMID 23834220, 2013). "Due to these nonepileptic events, molecular testing for episodic ataxia panel (CACNA1A, CACNB4, KCNA1, PNKD, PRRT2, SLAC1A3, VAMP1) was requested, and this came back normal." (PMID 37469362, 2023).